LRP5 (LDL receptor related protein 5)
Diseases named in the same sentence as LRP5 in open-access papers (continued):
Sharing a sentence is not in itself a finding about the gene and the disease.
juvenile osteoporosis (9 papers, 2012 to 2024). "The adult patient harboring only a DKK1 variant had a mild phenotype, in contrast to the female patient with severe juvenile osteoporosis with a combination of LRP5 and DKK1 variants, so the combination of two variants in the same pathway may accentuate the phenotype." (PMID 30283887, 2018). "Among the genes previously identified for low BMD, low‐density lipoprotein (LDL) receptor‐related protein 5 (LRP5) is a strong candidate contributing to idiopathic osteoporosis." (PMID 30283887, 2018). "Indeed, since cases of juvenile osteoporosis have been ascribed to inactivating mutations of the type 1 collagen (COL1A1), ERalpha (ERα), aromatase (CYP19), and low-density lipoprotein receptor-related protein 5 (LRP5) genes, the sequencing of these genes can be performed." (PMID 29058226, 2017).
Osteopenia (9 papers, 2012 to 2024). Osteopenia is a term to define bone density that is not normal but also not as low as osteoporosis. "More recently, mice expressing a high bone mass Lrp5 mutation not only prevented diabetic osteopenia but also improved peripheral glucose metabolism in a type I diabetes mouse model." (PMID 39434845, 2024). "The role of Lrp5 in bone formation is conserved between mice and human, as Lrp5 knockout mice develop osteopenia whereas mice carrying the Lrp5 hyperactive mutations (e.g., A214V) exhibit osteosclerosis." (PMID 34031510, 2021). "In the mouse, deletion of LRP5 either globally or specifically in bone causes osteopenia in the mouse, whereas expression of the high-bone-mass forms of LRP5 increases bone accrual." (PMID 24497849, 2014). "Mice lacking the Lrp5 gene, which codes for a Wnt coreceptor, developed osteopenia, while the overexpression of Lrp5 resulted in high-bone-mass syndromes." (PMID 34539793, 2021). "Interestingly, studies of the Lrp5-null mice also uncovered defects in glucose and cholesterol metabolism besides the expected osteopenia." (PMID 39434845, 2024). "Similarly, transgenic mice with interrupted Lrp5 express a low bone mass phenotype, independent of Cbfa-1, including decreased osteoblast proliferation, osteopenia and persistent embryonic eye vascularization." (PMID 22487062, 2012). "Mice lacking either Lrp5 or Lrp6 in mature osteoblasts displayed LBM and mice lacking both Lrp5 and Lrp6 in osteoblasts developed severe osteopenia." (PMID 29176883, 2017).
Hypercholesterolemia (8 papers, 2014 to 2025). An increased concentration of cholesterol in the blood. "Loss-of-function mutations in LRP5 have been found to result in abnormal glucose tolerance and hypercholesterolemia after a high-fat diet in animal studies due to a reduction in the levels of mRNA encoding insulin receptor, glucokinase, and HNF-4." (PMID 40940800, 2025). "Low-density lipoprotein (LDL) receptor- related protein 5 (LRP5) deficient mice were shown to have both hypercholesterolemia and bone mass reduction." (PMID 27738662, 2016). "LRP5 deficiency could prevent the calcification in the aortic valve under hypercholesterolemia condition." (PMID 34745206, 2021). "However, adult mice with LRP5 deficiency show low bone mass, impaired retinal vascularization, hypercholesterolemia, impaired insulin secretion and impaired mammary development, phenotypes that are also seen in patients with LRP5 loss-of function-mutations." (PMID 37091972, 2023). "Similarly in humans, LPR5-rs3736228T alleles that cause loss-of-function in LRP5 protein show increased plasmatic cholesterol levels in Chinese Han population 20 and is considered an independent risk factor for hypercholesterolaemia in the male Japanese population." (PMID 25656427, 2015). "Such supplements abolish hypercholesterolemia diet-induced LRP5 expression levels and decreases atherosclerotic plaque coverage in the aorta." (PMID 40940800, 2025). "Lrp5 mRNA expression in white blood cells showed a 77.5 ± 0.2% increase because of hypercholesterolaemia in Wt mice." (PMID 25656427, 2015). "However, LRP5 is active after hypercholesterolemia or ischemia, indicating that particular RNA splicing in the Lrp5 transcript must occur exclusively in the brains of Lrp5−/− mice to generate an Lrp5 transcript similar to full-length Lrp5-201 that can generate a functional protein." (PMID 38928468, 2024). "PBLs in young heterozygous genetically characterized FH patients have higher expression of LRP5 and LRP6 than age‐matched healthy controls or patients with secondary hypercholesterolaemia." (PMID 27680891, 2017). "Vldlr, a multiligand receptor that binds VLDL and chylomicron remnants 39 is not highly modified by mild hypercholesterolaemia or LRP5−/−." (PMID 25656427, 2015).
van Buchem disease (8 papers, 2010 to 2025). "We collected case reports of HBM with evidence of autosomal dominant transmission preceding the identification of the LRP5 mutations in 2002 (Worth-type endosteal hyperostosis) and cases of LRP5 HBM confirmed by genetic analysis since 2002." (PMID 37659026, 2023). "Other names include “autosomal dominant osteopetrosis, type 1”, “Van Buchem’s disease, type 2”, and more recently “LRP5 high bone mass (HBM)”." (PMID 37659026, 2023). "Cases were assessed clinically and underwent sequencing of known anabolic HBM loci: LRP5 (exons 2, 3, 4), LRP4 (exons 25, 26), SOST (exons 1, 2, and the van Buchem's disease [VBD] 52‐kb intronic deletion 3′)." (PMID 26348019, 2016). "As increasing numbers of individuals are reported, it is apparent that LRP5 HBM may not be as benign as first thought, and indeed shares many features with sclerosteosis and van Buchem’s disease —which is not particularly surprising given they share a common pathway." (PMID 33193107, 2020).
hepatocellular carcinoma (7 papers, 2014 to 2025). A malignant tumor that arises from hepatocytes. "In hepatoma cells, Wnt co-receptors LRP-5/6 and LRP-1, implicated in cell survival and invasiveness, were upregulated by SerpinB3." (PMID 37372056, 2023). "NUP37 is a major component of the nuclear pore complex, which regulates the stability of YAP1 in a LRP5-dependent manner and promotes the progression of hepatocellular carcinoma." (PMID 38304253, 2023). "Interestingly, LRP5 overexpression was shown to inhibit osteogenic differentiation in mesenchymal stem cells 40 and repression of canonical Wnt signalling has been described in poorly differentiated hepatocellular carcinoma cells." (PMID 24266894, 2014). "Our findings provide important insights into the roles of LRP5 and NUP37 in maintaining the integrity of the NPC and subsequent promotion of cancer progression in hepatocellular carcinoma (HCC)." (PMID 31881970, 2019).
Hyperglycemia (7 papers, 2011 to 2024). An increased concentration of glucose in the blood. "Recently, a gain-of-function Lrp5 mutation in insulin-deficient mice was shown to fully protect bone mass and strength in prolonged hyperglycemia, to improve peripheral glucose metabolism, and to prevent whitening of brown adipose tissue." (PMID 36947076, 2023). "In addition, promotion of LRP5 expression increased bone mass and bone strength in insulin-deficient diabetic mice, delaying the onset of hyperglycemia in these mice." (PMID 37106471, 2023). "Male mice with Lrp5 deletion in osteoblasts fed a high-fat diet also showed strong tendencies for hyperglycemia and insulin resistance." (PMID 37106471, 2023). "The observed overexpression in the placental sclerostin/LRP5 pathway in the studied GDM placentas might represent the development of an adaptive mechanism in face of maternal hyperglycemia." (PMID 36947076, 2023). "Several studies have speculated that hyperglycemia may be conferred by changes in LRP5 expression levels or tissue expression specificity, since LRP5 signaling contributes to the glucose-induced insulin secretion in the islets of Langerhans, however this mechanism is unclear." (PMID 30304114, 2018).
osteoarthritis (7 papers, 2011 to 2023). A noninflammatory degenerative joint disease occurring chiefly in older persons, characterized by degeneration of the articular cartilage, hypertrophy of bone at the margins and changes in the synovial membrane. "LRP5 is also associated with bone mineral density and with susceptibility to osteoarthritis." (PMID 21291537, 2011). "All of these findings suggest LRP-5 involvement in the increased activation of Wnt/β-catenin signaling and cartilage degradation in osteoarthritis." (PMID 22513174, 2012). "Our findings suggest, for the first time to our knowledge, that BMP-2-induced Wnt/β-catenin signaling activation through LRP-5 may contribute to chondrocyte hypertrophy and cartilage degradation in osteoarthritis." (PMID 22513174, 2012). "Recently, we showed that coreceptor of the Wnt/β-catenin signaling pathway, LRP-5, may have a catabolic role in osteoarthritis, as we observed significant upregulation of LRP-5 expression in osteoarthritic chondrocytes." (PMID 22513174, 2012). "Continuous activation of LRP5 may have additive toxicity resulting from the control of multiple genes and promote tissue fibrosis, various types of cancer and tumor metastasis, valve degeneration and calcification, and osteoarthritis." (PMID 30612120, 2019). "In addition, blocking LRP-5 expression in osteoarthritic chondrocytes resulted in a significant decrease in MMP-13 expression, the basic catabolic enzyme of osteoarthritis." (PMID 22513174, 2012).
osteogenesis imperfecta (7 papers, 2012 to 2024). Osteogenesis imperfecta (OI) comprises a heterogeneous group of genetic disorders characterized by increased bone fragility, low bone mass, and susceptibility to bone fractures with variable severity. "LRP5 HBM mutations are considered fully penetrant; however, phenotypes may vary even within an individual family, as is seen in many genetic conditions; eg, osteogenesis imperfecta." (PMID 26348019, 2016).
sclerosteosis (7 papers, 2010 to 2023). "The clinical phenotype of c.65T>C, p.Leu22Pro SMAD9 HBM has many features in common with that of LRP5 HBM but lacks the deleterious features that characterize SOST HBM (sclerosteosis)." (PMID 31525280, 2020). "Diseases of high bone mass are rare and include sclerosteosis due to deletion of SOST and autosomal dominant high bone mass due to gain-of-function mutations in LRP5." (PMID 22876197, 2012). "One model was mice with LRP5 human HBM missense gain-of-function mutations, LRP5A214V and LRP5G171V, knocked into the endogenous mouse Lrp5 locus, and the other model was mice with a loss-of-function mutation in Sost34 to model sclerosteosis." (PMID 37612291, 2023). "First, neither the LRP5 HBM patients nor those with Sclerosteosis are reported to have an increased rate of carcinogenesis." (PMID 20948575, 2010).
type 1 diabetes (7 papers, 2011 to 2023). "The human LRP-5 gene is mapped within the IDDM4 region, which is linked to type 1 diabetes (T1D) on chromosome 11q13." (PMID 22892353, 2012). "LRP5 was found to play an important role in glucose and lipid metabolism in animal studies and was located in the IDDM4 region in the long arm of chromosome 11, linked to type 1 diabetes." (PMID 26083111, 2015). "Our results suggest that analysed common variants in CTNNB1, AXIN2, LRP5 and LRP6 are not strongly associated with diabetic nephropathy in type 1 diabetes among white individuals." (PMID 21876774, 2011). "Our study was designed to assess association of common single nucleotide polymorphisms (SNPs) in four key genes of the canonical Wnt/β-catenin signalling pathway (AXIN2, CTNNB1, LRP5 and LRP6) with DN using a case-control design involving 1467 individuals with type 1 diabetes." (PMID 21876774, 2011).
Blindness (6 papers, 2009 to 2025). Blindness is the condition of lacking visual perception defined as a profound reduction in visual perception. "OPPG, a condition characterized by blindness and OP, is caused by mutations in the low-density lipoprotein receptor-related protein 5 (LRP5) gene." (PMID 40530681, 2025).
Hypertension (6 papers, 2014 to 2024). The presence of chronic increased pressure in the systemic arterial system. "In a recent study, LRP5 gene polymorphisms rs4988300 and rs3781590 were found independent genetic markers of AAA, even after adjusting for age, sex, dyslipidemia, hypertension, smoking habit, and chronic obstructive pulmonary disease." (PMID 24967416, 2014). "These correspond to LRP5 (which encodes Low Density Lipoprotein Receptor-Related Protein 5) and SERPINF1 (which encodes Pigment Epithelium Derived Factor (PEDF) belonging to Serpin Peptidase Inhibitors superfamily) respectively; and both contribute to hypertension." (PMID 29420653, 2018).
osteosclerosis (6 papers, 2014 to 2023). Abnormally high bone density. "“LRP5 mutation”, “high bone mass”, “osteopetrosis/osteosclerosis”, “ADO I” were used as key words to search for foreign literatures in the PubMed database." (PMID 36971833, 2023). "The characteristics of pathogenic genotypes and disease phenotypes of patients with osteosclerosis caused by LRP5 gain-of-function mutations were summarized, and to analyze whether there was a correlation between the genotypes and phenotypes." (PMID 36971833, 2023). "In addition, activating LRP5 mutations were identified in individuals with osteosclerosis, a high bone mass condition characterized by excessive bone formation." (PMID 26056589, 2014). "Likewise, mice carrying an HBM mutation within the Lrp5 gene display osteosclerosis, i.e. high bone mass due to excessive osteoblast activity." (PMID 26056589, 2014). "In contrast, other specific mutations in LRP5 affecting the binding of Dickkopf-1, an inhibitor of WNT signaling, result in gain-of-function of LRP5 and in osteosclerosis." (PMID 33919228, 2021). "This study identified two kinds of new mutations in LRP5 for the first time, of which the mutation in exon 3 may cause amino acid changes in the binding site of LRP5 with SOST, an antagonist protein in Wnt pathway, resulting in more severe phenotype of osteosclerosis." (PMID 36971833, 2023).
retinal detachment (6 papers, 2020 to 2024). An eye emergency condition which may lead to blindness if left untreated. "Retinal detachment is the most frequent symptom with patients of LRP5 and NDP mutations, accounting for 51.9% and 64.5%, respectively." (PMID 35830446, 2022). "According to our statistical analysis, it was found that the most common clinical manifestation of patients with LRP5 and NDP gene mutations was retinal detachment, which was the main cause of vision loss in FEVR." (PMID 35830446, 2022). "To this end, we suggest that once the patient is found with LRP5 and NDP mutations, it is necessary to always be alert to the occurrence of severe retinal detachment and lifelong monitoring should be carried out." (PMID 35830446, 2022). "No variations were noted in genes known to cause Wagner syndrome or other retinal detachments (ATOH7, TSPAN12, LRP5, or NDP) or in genes known to cause ocular disease." (PMID 33776059, 2021). "Hence, mutation in many components of the Wnt signaling such as Fzd-441, LRP5/642, Norrin43, or APC44 result in defective retinal vasculogenesis leading to compensatory neovascularization, vascular leakage, retinopathy of prematurity, retinal detachment, or in certain cases retinal coloboma." (PMID 33145027, 2020).
breast tumors (5 papers, 2009 to 2021). "Recently, a splice variant of Lrp5, ΔLrp5, was found in the majority (85%) of breast tumors, and was required for their continued growth." (PMID 19672307, 2009). "A truncated form of LRP5 has been found in more than 80% of breast tumors." (PMID 29854300, 2018). "The immunohistochemical results of breast tumors showed that CUMS upregulated the expression of β-catenin and LRP5 and promoted the phosphorylation of LRP5." (PMID 34912211, 2021). "We found that both LRP5 and LRP6 were more strongly expressed in TNBCs than in any other breast tumor subtype, consistent with published findings for LRP6." (PMID 29854300, 2018). "LRP5 and LRP6 although demonstrating a very similar expression profile within breast tumours have very different effects on recurrence." (PMID 23861811, 2013).
colon cancer (5 papers, 2018 to 2025). "Transgenic expression of ALOX15 suppresses TNF-α and iNOS expression as well as NF-κB activation and downregulates LRP5 to suppress Wnt/β-catenin signaling, thereby inhibiting colon cancer." (PMID 39334689, 2024). "By analysing the GSE34053 data set, we further confirmed that LRP5 mRNA level was upregulated in CD133+ CRC cells, compared with that in CD133− ones (p = 0.071) and carcinoma‐associated fibroblasts (p = 0.017) isolated from the same stage II colon cancer patient specimen." (PMID 34997691, 2022). "Strikingly, most of the Wnt genes upregulated by HMGA1 in our murine model are also upregulated in human colon cancer, including the WNT effectors, ASCL2, AXIN2, CTNNB1, MYC, EPHB2, CD44, and ETS2 and the WNT receptors, LGR5, LRP5, and LRP6." (PMID 39895630, 2025). "GO enrichment analysis showed that specific proteins, including TGFβ1, adenomatous polyposis coli (APC), CTNB1, low-density lipoprotein receptor-related protein (LRP) 5 (LRP5), LRP6, JAK1, ST14, and TP53BP1, were hypothetical CD151-interacting proteins in colon cancer." (PMID 33767593, 2021).
endosteal hyperostosis (5 papers, 2016 to 2025). "Worth syndrome, also known as autosomal dominant osteosclerosis and high bone mineral density, is a rare disease caused by a gain-of-function mutation of the low-density lipoprotein receptor-related protein 5 (LRP5) gene leading to endosteal hyperostosis." (PMID 40585686, 2025). "For example, mutations in the human Wnt co-receptor LRP5 are associated with several high bone mass syndromes including osteopetrosis type I, and endosteal hyperostosis or autosomal dominant osteosclerosis, as well as a low bone mass disease, osteoporosis-pseudoglioma." (PMID 34050174, 2021). "Mutations in the low-density lipoprotein receptor-related protein 5 (LRP5) gene, located on human chromosome 11q13.4, can lead to Worth syndrome." (PMID 40585686, 2025). "When consulting OMIM or the nosology of skeletal disorders, mutations in LRP5 are identified in patients diagnosed with high bone mass (HBM) phenotype, autosomal dominant osteopetrosis type 1, autosomal dominant Van Buchem disease, Worth disease, endosteal hyperostosis, or osteosclerosis." (PMID 32328030, 2020).